AXIN2 (axin 2)
Diseases named in the same sentence as AXIN2 in open-access papers (continued):
Sharing a sentence is not in itself a finding about the gene and the disease.
tumor (continued). "Expression analysis revealed a positive correlation between LINC00313 and TCF7, SULF2 and AXIN2 mRNA levels in resected tumours." (PMID 38332153, 2024). "Consistent with low WNT signaling in RevCSCs, BLM tumor stem cells had decreased expression of WNT/stemness-related genes compared to Min tumors such as Axin2, Id2, Sox4, Wnt6, Wnt10a, Id3, Prox1, and Id1." (PMID 38893159, 2024). "The PRC2 complex represses expression of AXIN2, activate Wnt/β-catenin pathway, and promote tumor development." (PMID 37880213, 2023). "We then isolated CD4+ T cells from the spleen, lymph nodes, and blood of healthy mice and tumor-bearing mice and investigated the expression of Tcf7, Lef1, and Axin2." (PMID 36239683, 2023). "Target engagement was demonstrated by inhibition of Axin2 expression in hair follicles and increased infiltration of T-cells into the tumor microenvironment." (PMID 35358569, 2022). "Molecular analysis indicated that the HCC tumours were indeed devoid of Rnf43/Znfr3 and expressed high levels of Axin2, confirming the Rnf43/Znrf3del origin of the tumour lesion." (PMID 35039505, 2022). "qRT-PCR analysis identified elevated expression of β-catenin target genes Axin2 and Lef1 in EdarTg951/951 tumour tissue, as well as elevated Edar transcript abundance when compared to untransformed EdarTg951/951 mammary tissue." (PMID 34916592, 2022). "KANK1 has also been reported to exert a tumor-suppressive effect by regulating the Wnt/β-catenin/Axin2 pathway in GC development." (PMID 35320976, 2022). "Since AXIN2 acts as an inhibitor of canonical Wnt signals in normal cells, many studies have focused on elucidating their role as tumor suppressors." (PMID 35550582, 2022). "CRC also up-regulates the expression of feedback inhibitors of the Wnt pathway, especially the putative tumor suppressor Axin2." (PMID 35836256, 2022). "Simvastatin treatment significantly inhibited transcript levels of LRP6 (1.69‐fold), AXIN2 (3.33‐fold) and Cyclin D1 (1.59‐fold), while we found a higher expression of the tumour suppressor APC levels compared to control." (PMID 35118811, 2022). "Similar increase was also observed in some of the key Wnt pathway genes such as CTNNB1, AXIN1 and AXIN2 suggesting a peak of immune exclusion in S2 tumours." (PMID 35301339, 2022). "While the expression of these proteins and TROAP‐induced tumor‐promoting effects (proliferation, migration and invasion) would be significantly reversed by silencing Axin2 or β‐Catenin." (PMID 34077623, 2021). "While earlier studies have suggested that Axin is a tumor suppressor, emerging evidence supports the important role of Axin2 in canonical Wnt and the Snail-mediated epithelial–mesenchymal transition (EMT)." (PMID 34298652, 2021). "Twenty-one days after TI-12403 treatment, we analyzed β-catenin and AXIN2 levels in tumor tissues of DLD-1 xenograft mice by immunohistochemistry assay." (PMID 34298950, 2021). "The absence of known Wnt regulators among our top candidates was surprising and thus we tested specific KO of APC and Axin2, two tumor suppressors which are core regulators of Wnt signaling." (PMID 34552058, 2021). "Next, qRT-PCR was conducted to determine the expression of circ_0038718, miR-195-5p and Axin2 in tumor tissue of nude mice, the result of which uncovered that miR-195-5p was markedly up-regulated while Axin2 was down-regulated upon circ_0038718 silencing." (PMID 34706645, 2021).
tumor (continued). "It is interesting to note that, ETV4, RNF43 and AXIN2 are highly correlated with tumour cell purity." (PMID 34824625, 2021). "The result unveiled that compared with the control group, tumor volume and weight in the si-NC + oe-Axin2 group were markedly increased, whereas those in the si-circ_0038718 + oe-Axin2 group were significantly decreased." (PMID 34706645, 2021). "As β-catenin was well studied as an important gene related to many cancers, the correlation between AXIN2 and tumor progression and metastasis have also been well reported by many studies in the past few decades." (PMID 33794810, 2021). "While the expression of the respective proteins and the CUX1-induced tumor-promoting effects (tumor cell proliferation and invasion) were significantly reversed by silencing Axin2 or β-Catenin expression (p < 0.05)." (PMID 34422906, 2021). "Although Axin1 has been widely regarded as a tumor suppressor, Axin2 plays a key regulatory function in the Snail-mediated EMT program and cancer progression caused by the nuclear-cytosolic shuttling of GSK-3." (PMID 34298652, 2021). "In both cohorts, differential AXIN2 expression was discriminatory between LD and LI tumours while EX tumours exhibited variable AXIN2 expression." (PMID 31563876, 2020). "Our analysis proved particularly informative when dissecting differences in transcriptome correlation between the four LEF/TCF genes and with AXIN2, comparing tumor with normal tissue samples." (PMID 32403323, 2020). "Next, to validate the accuracy of AXIN2 as a feasible biomarker for identification of LD tumours, we turned to two validation cohorts (Val-A/Val-B) derived from the S:CORT study." (PMID 31563876, 2020). "Glycogen synthase kinase 3β (GSK3β) and axis inhibition protein 2 (AXIN2) are negative regulators of Wnt signaling and are tumor suppressors in HCC." (PMID 33117795, 2020). "To further evaluate AXIN2 as a tumour biomarker, we wanted to assess both qRT-PCR and immunohistochemistry (IHC) as alternative approaches for scoring AXIN2 expression in a realistic clinical setting." (PMID 31563876, 2020). "Ω-3 PUFAs enriched diet suppressed the growth of MC38 colorectal carcinoma in mice, and treatment of tumours with epoxydocosapentaenoic acids, metabolites of ω-3 PUFAs, reduced expressions of protooncogens C-myc, Axin2 and C-jun in tumour tissues." (PMID 32526973, 2020). "Analysis of leading-edge genes within the NR signature identified five consensus differentially expressed NRs in the two discovery cohorts, all expressed at a significantly higher level in LI versus LD tumours—AXIN2, NKD1, APCDD1, NOTUM and DKK4." (PMID 31563876, 2020). "Among others, the expression of several genes such as Axin2, Ptn, Wif1, Clu and Wfdc18 was particularly characteristic for these tumor-specific cell clusters." (PMID 32080185, 2020). "Key Wnt negative regulator genes were differentially expressed between LD/LI tumours, with targeted hypermethylation of some genes (AXIN2, NKD1) occurring even in CIMP-negative LD cancers." (PMID 31563876, 2020). "AXIN2 mRNA expression was used as a discriminatory molecular biomarker to distinguish LD/LI tumours (area under the curve >0.93)." (PMID 31563876, 2020). "Tumour volume was significantly decreased in mice injected with Axin2-knockdown cells compared to both CA9–22 and HSC-2 control cells (A, i-ii)." (PMID 33046030, 2020). "The Wnt/β-catenin target genes Axin2, c-myc and Ccnd1 were also significantly decreased in WlsΔOB-OS tumor-bearing bones and primary OS cells, while endogenous c-fos and the c-fos transgene were not affected." (PMID 32686768, 2020). "Evidence for CRISPR/Cas Wnt7b gene inactivation is shown by the significantly reduced transcription of the canonical WNT signalling target Axin2 in edited tumour cells which can be rescued by WNT3a supplementation." (PMID 30926782, 2019).
tumor (continued). "The analysis confirmed a (moderate) increase in the expression of Ascl2 and other Wnt target genes Axin2, Lgr5, and SP5 in Apc/Msx−double-deficient tumor cells when compared to the cells with intact Msx1 gene." (PMID 30733598, 2019). "Reconstitution of Axin2 expression in miR-103/107-overexpressing cells blocked miR-103/107-induced tumor recurrence." (PMID 31273221, 2019). "Slit/Robo signalling has been shown to interact with the Wnt/β-catenin signalling in different types of tumour cells, and we found here that Robo1/2 KO pancreatic cells exhibit a reduced level of Axin2 expression but Lef1 appeared unchanged at E12.5." (PMID 30504829, 2018). "Because β-catenin is also a component for the cancer-promoting Wnt signaling that is intimately involved in tumor metastasis, we further examined the expression of β-catenin and Wnt target gene AXIN2." (PMID 30408026, 2018). "On the other hand, miR-4510 treatment led to an increase in several important regulators of β-catenin functions and tumor suppressors such as AXIN2, E-cadherin (CDH1), LRP1 and WNT5A." (PMID 28476031, 2017). "Axin 2 was also induced in tumor cells derived from recurrent tumors (RDR‐C234 and RDR‐A677) from the H1047R‐doxycycline‐inducible mouse model." (PMID 28296140, 2017). "In DPN, melanocytes demonstrated constant levels of AXIN2 expression throughout the neoplasm, whereas in common nevi AXIN2 expression decreased with distance from epithelium." (PMID 28935960, 2017). "Although earlier studies have suggested that Axin is a tumor suppressor, recent evidence supports the important role of Axin2 in canonical TCF/LEF activity as well as in Snail-mediated EMT progression." (PMID 28418862, 2017). "MiR-205 targets the axis inhibitor protein (Axin-2), a protein that functions either as tumor suppressor or as tumor promoter in different types of cancer." (PMID 29206174, 2017). "Our work reported here showed that SOX7 expression was correlated positively with AXIN2 and negatively with β-catenin, supporting our postulated synergy of SOX7 and AXIN2 to suppress tumor progression by promoting β-catenin degradation." (PMID 27188720, 2016). "GLI1 and AXIN2 were upregulated in the primary tumor and in two inoculation metastases compared to normal brain." (PMID 27825128, 2016). "Of note, the expression of Wnt target genes Axin 2, c-Myc, Cyclin D1 and survivin was significantly reduced in the tumor tissues treated with Bisleuconothine A sulfate, as well as the induction of Ser33/37/41 phosphorylation of β-catenin." (PMID 26862734, 2016). "This compound had a significantly improved IC50 (to nm level) and achieved good plasma and tumor exposure levels in mice, with a decrease in Axin2 mRNA levels as early as 4 hours post-treatment." (PMID 26246473, 2015). "In vivo, LY2090314 elevated gene expression of Axin2, a Wnt-responsive gene, and resulted in a tumor growth delay with repeat dosing in both single agent and combination drug studies." (PMID 25915038, 2015). "We also show that Wnt10bLacZ-driven tumours express high levels of β-galactosidase activity, have transcriptionally active nuclear β-catenin and correlating with high levels of AXIN2 protein expression." (PMID 23307470, 2013). "The homologous proteins AXIN1 and AXIN2 are components of the β-catenin destruction complex and thus, act as tumor suppressors by negatively regulating the Wnt signaling pathway." (PMID 23516639, 2013). "The Tcf1−/− tumor samples were clearly distinguished by factors involved in the Wnt-signaling pathway, Axin2, Lef1, and Tnfrsf19, or in the Notch signaling pathway, Deltex1 and Hes1." (PMID 23185135, 2012). "For only one gene (AXIN2), the level of methylation was significantly lower in tumour tissue compared with flat mucosa (P<0.001)." (PMID 18542073, 2008). "In several tumour types, TCF/β-catenin activation is caused by mutations in either adenomatous polyposis coli (APC), β-catenin exon 3, AXIN1, AXIN2 or β-transducin repeat-containing protein (β-TrCP)." (PMID 14970870, 2004).
tumor (continued). "Activated Wnt signalling in tumours is caused by increased levels of β-catenin, which can be the result of mutations in APC, β-catenin, AXIN1, AXIN2 or β-TrCP." (PMID 14970870, 2004). "shRNA-mediated knockdown of β-catenin in CT26-shApc cells led to a reduction in the expression of β-catenin target genes, including Axin2 and Lgr5, and inhibited tumor cell proliferation in both WT Balb/c and immunodeficient nude mice without affecting CD8+ T cell infiltration." (PMID 41486293, 2026). "Moreover, the negative correlation that we observed between retained 20AAR number and AXIN2 expression suggests that the APC genotype acquired early in tumorigenesis has lasting consequences on WNT levels throughout tumor progression." (PMID 41091816, 2025). "While in some studies, AXIN2 may have oncogenic properties, its role as a Wnt/β-catenin inhibitor and tumor suppressor is more widely recognized." (PMID 40746892, 2025). "We analyzed whether AXIN2 mRNA expression depends on SALL2 using non-tumor HEK293 and several CRC cell models." (PMID 40869218, 2025). "Contrary to its expected role as a tumor suppressor, Axin2 acts as a potent promoter of carcinoma behavior by enhancing the activity of the transcriptional repressor Snail1, triggering functional epithelial-mesenchymal transition (EMT) program and driving metastatic activity." (PMID 38534454, 2024). "Moreover, we measured increased SULF2 and AXIN2 expression in LINC00313 xenograft tumours, compared to control." (PMID 38332153, 2024). "We identified a tumor stem cell cluster (cluster 0) with Axin2, Sox4, Ccnd2, and Clu expression." (PMID 38893159, 2024). "Furthermore, the expression of EMT genes and oncogenes, including Mmp3, Mmp7, Mmp8, Fn1, Vim, Foxc2, Ctnnb1, Lgr5, Axin2, cMyc, Ccnd1, and Yap1, was significantly high in the tumor of cohoused Nlrp12–/– compared with WT mice." (PMID 37581937, 2023). "In particular, AXIN2 has been described as a strong tumor promoter for CRC in vivo by inducing EMT." (PMID 35565214, 2022). "In addition, epigallocatechin-3-gallate can inhibit cell proliferation and the formation of oncospheres enriched with tumor stem cells at 40 μM by downregulating the levels of Axin2, c-Myc, and Cyclin D1 and PCNA." (PMID 35053565, 2022). "Wnt-target gene (Axin2, Myc and Lgr5) expression was increased in the small intestine tumour tissue compared to normal tissue from both ApcMin/+/Setd7−/− and ApcMin/+/Setd7+/− mice, but more in tumours from ApcMin/+/Setd7+/−." (PMID 35326563, 2022). "Notably, classical Wnt target genes Axin2 and Birc5 (also known as Survivin) were significantly up-regulated only in late-passage Apc+/−;Bmal1−/− organoids that grow as tumor spheroids." (PMID 35947664, 2022). "The variant rs2240308 (p.Pro50Ser) is located near the RGS domain (regulator of G protein signalling; amino acids 81–200), which involves the APC-binding site and participates in the tumor suppressor function of AXIN2 through the assembly of the β-catenin destruction complex." (PMID 35996498, 2022). "However, ETV4, RNF43 and AXIN2 were clustered with tumour purity and separate from all other infiltrating cell types." (PMID 34824625, 2021). "TFRC has been reported to promote tumor migration via the positive regulation of AXIN2." (PMID 34151031, 2021). "For the biological function, AXIN2 is a critical regulator in Wnt/β-catenin signaling, especially for the stability of β-catenin, which plays an important role in cell growth, genesis of a number of malignancies, tumor progression and so on." (PMID 33794810, 2021). "The expression of these proteins and the CUX1-induced tumor-promoting effect could be reversed by silencing Axin2 or β-catenin expression." (PMID 34422906, 2021).
tumor (continued). "Knockdown of Axin2 could also attenuate the promoting effect of high circ_0038718 expression on CC cell malignant progression, thus inhibiting tumor growth." (PMID 34706645, 2021). "As a result of this work, AXIN2 hypermethylation/silencing is proposed as a tractable biomarker of ligand-dependent tumours that may help prospectively stratify patients for therapies perturbing Wnt-pathway ligands, including PORCN inhibitors." (PMID 33673710, 2021). "Moreover, in the mouse xenograft analysis, the stromal component of tumour nodules as well as the osteolytic bone resorption of mouse calvaria were predominantly decreased in the group of cells with Axin2 knockdown compared to control cells." (PMID 33046030, 2020). "The data from TCGA showed that AXIN2 was upregulated in CRC tumor tissues." (PMID 32258125, 2020). "Due to limitation of available tumour samples, qRT-PCR analysis could only be performed on two WNT signalling target genes (Wif1 and Axin2) using RNA from two Apc2-deficient GCTs, with Apc2-proficient ovaries used as control material." (PMID 31291912, 2019). "AXIN2 has been shown to behave as both a tumor suppressor and an oncogene." (PMID 31382613, 2019). "Reexpression of Axin2 in miR-103/107-overexpressing cells blocked the ability of miR-103/107 to increase nuclear β-catenin and to stimulate the formation of tumor spheres." (PMID 31273221, 2019). "As an important tumor suppressor, the level of Axin2 can be increased by KIF5C." (PMID 31844033, 2019). "The level of Axin2, an important tumor suppressor, can be increased by inhibiting KIF5C." (PMID 31844033, 2019). "However, in vivo findings also suggest AXIN2 as tumor-promoting, as it upregulates the transcriptional repressor, SNAI1, leading to increased EMT and metastatic activity in colorectal cancers in mice." (PMID 31382613, 2019). "Axin2 is a tumor suppressor that is induced upon activation of Wnt/beta-catenin pathway." (PMID 31258833, 2019). "Furthermore, miR-103/107-induced tumor-initiation capability was also suppressed by Axin2 reexpression." (PMID 31273221, 2019). "Moreover, mRNA levels of the Wnt target genes CCND1, AXIN2 and c-Myc were dramatically decreased in the tumor with low TGIF1 levels." (PMID 29050273, 2017). "In the same model treatment with GDC-0449 showed no anti-tumor efficacy and was associated with increased AXIN2 expression at the end of the study." (PMID 27750213, 2017). "In this system, they reported a moderate upregulation of classic Wnt pathway targets, such as Lgr5 and Axin2 in the intestine, spheroid changes in organoids, and a tumour response driven predominantly by paracrine Rspo3 signals from a minor sub-population of cells." (PMID 28695896, 2017). "By immunohistochemistry, we have revealed a significant increase in the expression of β-catenin and two known downstream targets of Wnt/β-catenin pathway cyclin D1 (CCND1) and Axin2 in the tumor tissues of the ApcMin/+;Slit2 and DMH/DSS-Slit2 mice, as opposed to their respective controls." (PMID 25605242, 2015). "The AXIN2 protein acts as a tumor suppressor in numerous cancers." (PMID 26161041, 2015). "Axin2 negatively regulates Wnt signaling and acts as a tumor suppressor protein." (PMID 25013500, 2014). "Also, a tumor cell line with high methylation (HCT116) exhibited lower expression of AXIN2 than another cell line (Caco2) with little methylation." (PMID 24964857, 2014). "Therefore, Axin2 acts as a master scaffold protein in Wnt signaling, and is one of the tumor suppressor proteins." (PMID 25013500, 2014). "The mean expression Axin2 level of the 40 tumor samples was 4 times elevated compared to the mean expression Axin2 level of the control mice (1.2 versus 0.3), with 29 of the 40 tumor samples (73%) having a higher Axin2 level than 0.3." (PMID 23185135, 2012).